HLA-C (major histocompatibility complex, class I, C)
Diseases named in the same sentence as HLA-C in open-access papers (continued):
Sharing a sentence is not in itself a finding about the gene and the disease.
cancer (684 papers, 2004 to 2026). A tumor composed of atypical neoplastic, often pleomorphic cells that invade other tissues. "Studying the alleles and structural variants of HLA-C seems very relevant to understanding the aggressiveness of different types of cancer." (PMID 37465164, 2023). "Most notably, multiple HLA-C*08:02-restricted TCRs specific for the oncogenic hotspot mutation KRAS-G12D were identified in several cancer patients." (PMID 35587797, 2022). "The HLA-A*25 and HLA-C*06 alleles exhibited a significantly higher frequency in cancer patients than in the normal population of 174 blood and kidney donors (p = 0.02 and p = 0.01, respectively, Fisher’s exact test)." (PMID 35954492, 2022). "We also observed lower expression of MHC-I genes on EMM cells (HLA-B, HLA-C), which may be associated with reduced efficacy of cancer immunotherapies due to decreased recognition of malignant cells by effector T cells." (PMID 38493239, 2024). "We also found that 20 neoantigens occurring in more than 80% of NDMM samples were preferentially presented by HLA-C alleles, suggesting neoantigens presented by HLA-C alleles could be prioritized for cancer vaccine development." (PMID 34504297, 2021). "Conversely, major histocompatibility complex (MHC) class I molecules (HLA-A, HLA-B, HLA-C) were progressively downregulated, a common immune evasive strategy by cancer cells to thwart immune detection and clearance." (PMID 40858992, 2025). "The transition areas (II) that encompass both cancer cells and immune cells as defined in the original study exhibit high expression of FTL, CTSB, and HLA-associated genes (e.g., HLA-A, HLA-B, HLA-C), indicating immune infiltration in the TME." (PMID 40033360, 2025). "(F) RT-qPCR quantification of HLA-A, HLA-B, and HLA-C mRNA levels in cancer cell lines after 24 hr BQ treatment." (PMID 38973593, 2024). "This confirmed that MHC-I heavy chain transcripts (HLA-A, HLA-B, and HLA-C) are consistently upregulated in response to BQ across diverse cancer types." (PMID 37066260, 2024). "Collectively, 11C/73- and 2C/165-expressing T cells specifically and efficiently recognized CSPG4+HLA-C*07:01+ cancer cells which warrants further preclinical and clinical evaluation of these TCRs." (PMID 37849763, 2023). "The top five ligands targeting CD8+ T-cells by mesenchymal cancer cells from infiltrated tumors were HLA-C, HLA-A, CD59, LGALS3, and B2M." (PMID 38086828, 2023). "There is a paradoxical role for HLA-C in oncological pathologies, as evidence shows both low and high-expression gene correlations with various types of cancer." (PMID 37465164, 2023). "Exome array CRC case–control analysis followed by functional validation demonstrated that HLA-C likely exerts its influence on CRC development via cancer-related signaling pathways." (PMID 35379174, 2022). "The lower expression levels of HLA-C were evidently observed in five different CRC cell lines than in non-cancer colorectal cell line." (PMID 35379174, 2022). "Some of these genes such as HLA-E and HLA-C are directly related to MHC-I signaling by the cancer cell." (PMID 36230778, 2022). "Since our study demonstrated that the expression level of HLA-C is higher in non-cancer colorectal cells than in CRC cells, we assumed that the proliferation of CRC cells is decreased by overexpressing HLA-C in CRC cells." (PMID 35379174, 2022). "Pathway analysis detected that significantly down-regulated genes in HLA-C overexpression CRC cells were highly enriched in cancer-related signaling pathways such as JAK/STAT, ErbB, and Hedgehog signaling pathways." (PMID 35379174, 2022). "Cell viability tests using Ez-cytox demonstrate that HLA-C overexpression in cancer cells reduces cell viability." (PMID 35379174, 2022). "To understand the underlying mechanism exerted by HLA-C in CRC development, we conducted RNA sequencing analyses of HLA-C overexpression CRC cells and non-cancer colorectal cells." (PMID 35379174, 2022).
cancer (continued). "HLA-C instead shows more mutations in the peptide-binding groove, and it is interesting to note that HLA-C is the major inhibitory ligand for killer immunoglobulin-like receptors (KIRs), which might help to explain why viruses and cancers target this haplotype differently." (PMID 33784856, 2021). "MiR-9 has the potential to downregulate MHC-I molecules (i.e. HLA-H, HLA-B, HLA-C, and HLA-F) and its overexpression in cancer cells enhances immune tolerance in the TME." (PMID 34122412, 2021). "In a large HNSCC patient cohort published by the TCGA cancer atlas (n = 515), 9% (45/515 of all HNSCC patients have somatic mutations in the MHC class I heavy chain genes (HLA-A, HLA-B, and HLA-C), or the MHC class I light chain gene (β-2 microglobulin, B2M)." (PMID 31614809, 2019). "The MHC-I complex aids in the presentation of cancer neoantigens to CD8+ cells, and variability among the genes encoding it, including B2M and the HLA-I genes (HLA-A, HLA-B, and HLA-C), has been demonstrated to influence ICB response." (PMID 30497521, 2018). "The results from the five-gene signature (adding two genes: TCF7L2 and HLA-C) showed 13 different cancer studies." (PMID 30287838, 2018). "Our analysis also identified several antigen-presenting molecules as potential cancer drivers, including one class I (HLA-C), one class II (HLA-DRB1), and three HLA-like proteins (CD1C, CD1E and MR1)." (PMID 26485003, 2015). "Multivariate analysis revealed that expression of HLAA, HLAB, and HLAC were all significantly less in MSI-H than MSS cancers (p = 0.027, p = 0.017, and p = 0.018, respectively for HLA-A, B and C), consistent with previous observations." (PMID 25949894, 2015). "From the MSigDB Cancer Neighbourhood Ontology, we found that the GM-enriched binding windows were in proximity to cancer-associated genes, CD53, VAV1, INPP5D, STAT6, HLA-C, etc." (PMID 25522020, 2014). "We show that NK cell activation and induction of the relevant lysis receptors, as well as co-administration of antibodies yield substantial anti-cancer effects, which are functionally superior to HLA-C mismatching." (PMID 23483943, 2013). "A central question is whether the cancer type specific hierarchy of HLA class I gene (HLA-A, HLA-B, and HLA-C) expression observed in the CCMA cohort is preserved in primary tumors." (PMID 41312385, 2025). "The effector functions of NKG2C have largely been demonstrated in the context of viral infections, however, they may also operate in cancer as NKG2C+ NK cells have recently demonstrated potent cytotoxicity against HLA-C:KIR mismatched leukemic cells." (PMID 38223411, 2024). "For instance, IPH2102 was used to inhibit inhibitory signaling of NK cells by preventing inhibitory KIRs from binding to HLA-C of cancer cells, thus activating ADCC mechanisms to kill the cancer cells that had been marked with cetuximab during head and neck immunotherapy." (PMID 38726000, 2024). "In addition, we observed decreased expression of MHC-I molecules HLA-B and HLA-C in EMM cells, a phenomenon previously associated with a worse response to immunotherapy in other types of cancer." (PMID 38493239, 2024). "We found that HLA-A and HLA-B showed higher HED than HLA-C in cancer patients." (PMID 36177028, 2022). "The consequences of our findings may have broad implications for T cell recognition of HLA-C beyond the specific example of KRAS-G12D recognition in cancer." (PMID 35587797, 2022). "RNA-seq analysis suggests that overexpressed HLA-C reduces cell proliferation and the cell cycle by down-regulating signals in cancer-related pathways such as cytokine-cytokine receptor interaction, the JAK/STAT signaling pathway, the ErbB signaling pathway, and the Hedgehog signaling pathway." (PMID 35379174, 2022). "Furthermore, it is inferred that HLA-C overexpression has the potential to protect against cancer or improve prognostic outcome." (PMID 35379174, 2022).
cancer (continued). "HLA-I (MHC-I), of great importance, consists of a highly polymorphic α-heavy chain and a β2-microglobulin (β2M) light chain, encoded by the HLA-A, HLA-B, or HLA-C genes, delivers peptides to CD8+ T cells, and is essential for immune surveillance and cancer immunotherapy." (PMID 34805135, 2021). "Therefore, we developed a MHC-multimer double-staining approach against a cancer epitope-specific HLA-C*07:02 multimer to identify truly HLA-C*07:02/IE-1 epitope-specific T cells." (PMID 29489900, 2018). "Indeed, the expression of MHC class I molecules (HLA-A, HLA-B, and HLA-C) on cancer cells allows their detection and destruction by T cell lymphocytes." (PMID 29930758, 2018). "Although no data have been published on an association between NSCLC and HLA-C so far, we may speculate that the C1C2 genotype may allow for a wider spectrum of KIRs to contribute to control over cancer cells." (PMID 20865034, 2010). "Moreover, CD247, CD3G, HLA‐B, HLA‐C, and HLA‐F took part in various pathways, including Th1 and Th2 cell differentiation, PD‐L1 expression and PD‐1 checkpoint pathway in cancer, Th17 cell differentiation, antigen processing presentation, allograft rejection, and cell adhesion molecular." (PMID 35037412, 2022). "While the roles of C4BPB, HLA-C, and SERPINB1 in cancer immunobiology have been increasingly recognized, direct evidence of their function in PDAC remains limited." (PMID 41007761, 2025). "To achieve a comprehensive and objective evaluation of MHC-I expression in cancers, we developed a MHC-I signature score based on GSVA of eight MHC-I family genes, including HLA-A, HLA-B, HLA-C, HLA-D, HLA-E, HLA-F, HLA-H, and B2M." (PMID 39408874, 2024). "Of these genes, TAP2, B2M, IRF1, TAP1, HLA-A, HLA-B and HLA-C were formally and independently classed as CRC drivers, with strongest signals in MSI cancers, but also discovered in MSS cancers (for example, HLA-A and B2M)." (PMID 39112709, 2024). "Consistent with our finding, individual cancer-specific EMT signature genes such as PDIA3, HLA-A, BCAM, B2M, LGALS3BP, and HLA-C were highly expressed in cancer cells from infiltrated and excluded TMEs." (PMID 38086828, 2023). "By incorporating the weak genes CSNK2B, HLA-A, HLA-C, and HLA-DRA, the PD-1, PD-L1 cancer immunotherapy pathway was significantly enriched." (PMID 37065470, 2023). "Of these genes, only HLA-C consistently showed the differential expression in different CRC cell lines (such as Caco-2, DLD-1, HCT116, HT-29, and SW480) compared to non-cancer colorectal cell line (CCD-18co)." (PMID 35379174, 2022). "Myeloid cell-cancer cell communication analyses revealed activation of C5AR1/RPS19 and HLA-C/FAM3C pairs." (PMID 34326696, 2021). "We used the PLK1 inhibitor (BI2536) to treat cancer cell lines and compared expression levels of MHC class I (HLA-A, HLA-B, HLA-C, B2M, and TAP1 genes and their protein products) between the pre- and post- treated cell lines." (PMID 30631355, 2018). "NK cells' cytotoxic activity is mediated by the level of expression of MHC molecules—HLA-A, HLA-B, and HLA-C—and KIR receptors on cancer cells." (PMID 30425720, 2018). "Noteworthy were a number of hub genes like TLR4, FAS, HLA-DQB1, HLA-DQA1, F2, HLA-C, IFNAR1, which link complex diseases related to metabolic, immunological, infectious, cardiovascular, neuro-psychiatric disorders and cancer." (PMID 18782426, 2008). "Thus, the C1/C2 dimorphism on its own impacts peptide presentation and HLA-C-restricted T cell responses, with implications in disease, including adoptive T cell therapy targeting KRAS-G12D-induced cancers." (PMID 35587797, 2022). "Indeed, we observed that HLA-C overexpression reduces cell viability in CRC cells, in which the expression of HLA-C was initially lower than in non-cancer colorectal cells." (PMID 35379174, 2022).
cancer (continued). "There are classical forms, HLA-A, HLA-B, and HLA-C, and non-classical forms, HLA-G, HLA-E, HLA-F, and HLA-H, of this protein; both have been identified in cancer with diverse roles." (PMID 34359613, 2021). "Since NK cells are implicated in the antitumoral immune response, this could indicate that HLA-C gene variations, with or without accompanying KIR polymorphisms, could affect cancer risk development." (PMID 38680423, 2024). "Interestingly, ANGPTL2 mRNA levels show a significant positive correlation with those of JARID2 mRNA, and levels of both are negatively correlated with those of HLA‐B and HLA‐C mRNAs in cancer lines derived from metastatic rather than primary lesions." (PMID 37452654, 2023). "In another cancer—neuroblastoma, the presence of individual KIR genes, KIR2DL2 and KIR2DS2, regardless of the HLA-C genotype, may predict treatment outcomes." (PMID 34359951, 2021).
infection (320 papers, 2005 to 2026). The state of being infected such as from the introduction of a foreign agent such as serum, vaccine, antigenic substance or organism. "This supports that HLA-B*38 and HLA-C*03 alleles play a protective role in L. infantum infection, both in terms of protection against infection and in the development of asymptomatic disease." (PMID 39125781, 2024). "The 8- and 9-mer peptides show P2 enrichment for Ser, Thr, and Ala in peptides differentially bound by HLA-C alleles encoded by patients with severe versus mild infection." (PMID 39337964, 2024). "We show a possible association between HLA-B*38 and HLA-C*03 alleles and protection against infection, which should be confirmed with larger cohorts to obtain greater statistical power." (PMID 39125781, 2024). "For example, in EUR ancestral group, HLA-B*27:05 were associated with an overall decreased risk of infection, HLA-A*11:01 were associated with less severity, while HLA-C*12:03, -B*35, -B*38:01 were associated with an increased risk of SARS-CoV-2 severity." (PMID 36649279, 2023). "In the case of ZiKV, infection of extravillous trophoblasts causes ER stress that results in the downregulation of HLA-C and -G, which renders these cells susceptible to killing by decidual NK cells." (PMID 35401580, 2022). "The mechanisms by which activating KIR and HLA-C interactions reduce the risk of pregnancy complications and enhance immunity to infections during pregnancy should be investigated in more molecular detail." (PMID 31921098, 2019). "- What are the molecular and cellular mechanisms by which activating KIR and HLA-C interactions reduce the risk of pregnancy complications and enhance immunity to infections?" (PMID 31921098, 2019). "For one donor sampled at 1, 4 and 10 years post-infection, the 5 most frequent Vpu sequence variants observed at each time-point were studied, and showed variation in HLA-C downregulation between the viral quasi-species present at all timepoints." (PMID 30180214, 2018). "A single-nucleotide polymorphism (SNP) in the HLA-C gene affects post-infection outcome by influencing surface expression of HLA-C protein." (PMID 30534128, 2018). "The protective role of highly expressed alleles towards infection is in apparent contrast with our results, which show a role for the Env/HLA-C association in enhancing viral infectivity." (PMID 28051183, 2017). "Genetic variants of KIR2DS4, KIR2DS1, KIR2DL1, and HLA-C increase susceptibility to infection." (PMID 40244151, 2025). "We also orthogonally classified HLA-C alleles based on the complete peptide binding groove amino acid composition and found that clusters with higher promiscuity in peptide binding were associated with more severe infection." (PMID 39337964, 2024). "Specifically, we analyzed the association of HLA-B*38 and HLA-C*03 alleles with infection." (PMID 39125781, 2024). "The proportion of known (defined) HLA-C-restricted CTL epitope variants had also increased from 20.8% to 33.3% at one year post infection in those subjects that possessed the restricting HLA-C alleles, compared to an increase from 20% to 21% in those without the restricting HLA-C alleles." (PMID 25781986, 2015). "Interestingly, the variant epitope proportion in individuals possessing the restricting HLA allele was found to have increased more substantially for HLA-C alleles (from 37.5% at early infection to 58.3% at one year post infection." (PMID 25781986, 2015). "Genome-wide association studies (GWASs) have revealed several genetic loci associated with HIV-1 outcome following infection (e.g., HLA-C at 6p21.33) in multi-ethnic populations with genetic heterogeneity and racial/ethnic differences among Caucasians, African-Americans, and Hispanics." (PMID 26039976, 2015). "However, since KIR2DL1/HLA-C*04 interaction was associated with a higher rate of relapse, immunosuppression caused by intensification treatments could be the main reason for infection and death." (PMID 34064810, 2021).